INO80B (INO80 complex subunit B)
Description:
Induces growth and cell cycle arrests at the G1 phase of the cell cycle. Proposed core component of the chromatin remodeling INO80 complex which is involved in transcriptional regulation, DNA replication and probably DNA repair.
Synonyms: hIes2; PAPA-1; HMGA1L4; PAPA1; ZNHIT4; HMGIYL4; PAP-1BP; IES2
Tractability: Small molecule: a structure with a bound ligand is known. PROTAC: its protein half-life has been measured.
Gene: Protein-coding gene on chromosome 2 (74,455,087 to 74,457,944, forward strand). Ensembl gene ENSG00000115274.
Subcellular location: Nucleus; Nucleus, nucleolus
Subcellular location (Human Protein Atlas): Nucleoplasm; Nuclear bodies; Nucleoli
Pathways (Reactome):
DNA Repair: DNA Damage Recognition in GG-NER
Metabolism of proteins: UCH proteinases
Gene Ontology:
Molecular function: protein binding
Biological process: chromatin remodeling; positive regulation of DNA-templated transcription; regulation of cell cycle; regulation of chromosome organization; regulation of DNA replication; regulation of DNA strand elongation
Cellular component: Ino80 complex; nuclear body; nucleolus; nucleoplasm; nucleus
Genetic constraint (gnomAD): Loss-of-function variants: 16 observed, 25.49 expected, observed/expected ratio (o/e) 0.63, 90% interval 0.42 to 0.95. The synonymous counts are far from expectation, so gnomAD's model fits this gene poorly and the ratio says little. Missense variants: 468 observed, 437.49 expected, observed/expected ratio (o/e) 1.07, 90% interval 0.99 to 1.15. Synonymous variants: 237 observed, 176.69 expected, observed/expected ratio (o/e) 1.34, 90% interval 1.21 to 1.49.
Homologues: Orthologues: chimpanzee INO80B (99% identical), macaque INO80B (99% identical), dog INO80B (97% identical), pig INO80B (97% identical), guinea pig INO80B (95% identical), mouse Ino80b (95% identical), rat Ino80b (94% identical), zebrafish ino80b (52% identical).
Diseases named in the same sentence as INO80B in open-access papers:
INO80B is named in the same sentence as 1 disease in open-access papers, as found by Europe PMC text mining. Sharing a sentence is not in itself a finding about the gene and the disease. The quoted sentences say what the papers report.
personality disorder (1 paper, 2022). A diverse category of psychiatric disorders characterized by behavior that deviates markedly from the expectations of the individual's culture; this pattern of deviation is pervasive and inflexible and is stable over time. "INO80B regulates trophoblast differentiation and embryonic stem cell self-renewal, implicating in tumorigenesis, pre-eclampsia, and avoidant personality disorder." (PMID 36062142, 2022).